EGFR (epidermal growth factor receptor)
Diseases named in the same sentence as EGFR in open-access papers (continued):
Sharing a sentence is not in itself a finding about the gene and the disease.
HCMV infection (continued). "The intertwining of integrin, specifically β1 and β3, and EGFR signaling has been shown to be critical for HCMV infection of monocytes." (PMID 30127257, 2018). "Collectively, this work demonstrates a pivotal role for EGFR and virus-mediated control of EGFR signaling in regulating replicative and latent states during HCMV infection." (PMID 30127257, 2018). "We conclude that (i) EGFR trafficking is impeded by CMV infection, (ii) UL135 impedes recovery of EGFR at the cell surface, and (iii) pUL138 impedes internalization or stimulates rapid recovery of EGFR to the cell surface during early times post EGF." (PMID 27218650, 2016). "We propose a model whereby pUL135 and pUL138 together with EGFR comprise a molecular switch that regulates states of latency and replication in HCMV infection by regulating EGFR trafficking to fine tune EGFR signaling." (PMID 27218650, 2016). "Upon HCMV infection in fibroblasts, viral glycoproteins gB and gH independently bind to EGFR and αvβ3 integrin, respectively, to initiate viral entry and signaling." (PMID 21994732, 2011). "Additionally, the epidermal growth factor receptor (EGFR) is thought to mediate HCMV infection by interacting with gB and activating downstream signaling pathways such as PI3K." (PMID 39585514, 2024). "Thus, the combination of UL135 or UL135 with EGFR represents a molecular switch that regulates the latency or reactivation of HCMV infection." (PMID 38136637, 2023). "Downregulation of EGFR expression is a characteristic of HCMV infection." (PMID 38136637, 2023). "However, the role of EGFR in HCMV infection is controversial and depends on the virus strain or cell line specificity." (PMID 38136637, 2023). "Next, by KEGG pathway enrichment analysis, we found that the 6 core target genes were mainly enriched in the EGFR tyrosine kinase inhibitor (EGFR-TKI) resistance, Kaposi sarcoma-associated herpesvirus (KSHV) infection, and human cytomegalovirus (HCMV) infection pathways." (PMID 35707473, 2022). "HCMV infection of monocytes triggers a rapid and sustained activation of Akt, which occurs when viral glycoprotein gB interacts with epidermal growth factor receptor (EGFR) on the surface of monocytes during viral entry." (PMID 32560319, 2020). "Interestingly, CMV infection of CD34+ HPCs results in a transient increase in surface expression of EGFR early on in infection." (PMID 30127257, 2018). "Initial studies implicated the epidermal growth factor receptor (EGFR) as a receptor for HCMV entry into fibroblasts in 2003, with gB shown to bind directly to EGFR, leading to downstream signalling events that were required for efficient HCMV infection." (PMID 29547547, 2018). "While the increase in EGFR expression induced by CMV infection of CD34+ HPCs in vitro was transient, this may reflect limitation of CD34+ culture." (PMID 27218650, 2016). "The discrete association of EGFR with Rab5 and Rab11 vesicles in the context of infection suggests that CMV induces the accumulation of EGFR in vesicles poised for its recycling during CMV infection." (PMID 27218650, 2016). "In betaherpesvirus HCMV infection, EGFR serves as a receptor and αvβ3 integrin as a coreceptor." (PMID 21994732, 2011). "However, other studies dispute the role of EGFR as a receptor necessary for HCMV infection." (PMID 31356650, 2019). "The changes in EGFR signaling in CD34+ HPCs may explain some of the infection-induced alterations in myeloid differentiation, as levels of the inflammatory cytokine interleukin-12 are increased during CMV infection and further exacerbated by inhibition of EGFR signaling." (PMID 30127257, 2018). "However, the association of Rab5 and Rab11 with EGFR was increased in the context of CMV infection." (PMID 27218650, 2016). "HCMV miR-US5-2 is a critical modulator that targets GAB1, attenuates EGFR signaling pathways, and interferes with EGR1 and HCMV UL138 expression during HCMV infection." (PMID 38136637, 2023).
HCMV infection (continued). "EGFR also acts as a determinant in the selection of hematopoietic cells for HCMV latency tropism and is important in the early stages of successful HCMV infection." (PMID 38136637, 2023). "Particularly notable was the downregulation of the RTK EGFR, which was also observed after HSV-1 and HCMV infection." (PMID 35727847, 2022). "During HCMV infection, we find PTPN1, which deactivates EGFR at ER-endosome MCSs60, increasing in sync with EGFR downregulation." (PMID 35953480, 2022). "Using these vectors, we found that overexpression of EGFR and PDGFRα in hiPSCs, which are resistant to HCMV infection, rendered these cells permissive to TB40/E infection, supporting the idea that both EGFR and PDGFRα are important mediators of HCMV infection." (PMID 33205055, 2020). "Epidermal growth factor receptor (EGFR) activation by HCMV and its interaction with gB have been reported to play a role, potentially as a receptor, in HCMV infection." (PMID 31356650, 2019). "However, papers that attempted to recapitulate the noted ability of anti-EGFR antibodies and chemical inhibitors of EGFR signalling such as AG1478 to inhibit HCMV infection failed to do so, causing us to question the role of this RTK as a bona fide entry receptor." (PMID 29547547, 2018). "The binding of WT1 to the EGFR promoter also increases during HCMV infection, while depletion of WT1 suppresses HCMV-induced negative regulation of EGFR." (PMID 38136637, 2023). "Several molecules, such as EGFR, Integrin αvβ3, CD90, CD147, Neuropilin-2, and platelet-derived growth factor receptor alpha (PDGFRα), have been identified as receptors or co-receptors for HCMV infection in fibroblasts, epithelial, or endothelial cells." (PMID 37146061, 2023). "The regulation of EGFR during CMV infection likely reflects a fine-tuning of host signaling, not an all or none event." (PMID 27218650, 2016). "Therefore, while CMV infection affects multiple RTKs during infection, UL135 and UL138 appear to have some specificity for EGFR." (PMID 27218650, 2016). "EGFR- or PDGFR-negative cells are not permissive to HCMV infection, but expression of EGFR or PDGFR renders these cells susceptible to HCMV." (PMID 25805993, 2015). "The observation that cells expressing neither PDGFR- α nor EGFR are still permissive for HCMV infection implies that the virus exploits additional host factors at an early step of infection." (PMID 26147640, 2015). "Therefore, THY-1 may be part of a multimolecular complex mportant for the initial phase of CMV infection and signaling (that includes PDGFR- α, EGFR, integrins, paxillin, and viral glycoproteins)." (PMID 26147640, 2015).
meningioma (41 papers, 1991 to 2026). A generally slow growing tumor attached to the dura mater. "The experimental results showed that, compared to the control group, NF2‐associated meningioma cells exhibited increased expression of EGFR, indicating enrichment of EGFR in NF2‐associated meningioma cells." (PMID 38828669, 2024). "The association of EGFR vIII and meningioma grade is a potential new avenue for therapeutic intervention, either as adjuvant treatment or in combination with radiation therapy." (PMID 34582442, 2021). "Overexpression of EGFR in meningioma is well observed but role of its mutated form in still in question." (PMID 34582442, 2021). "The pharmaceutical inhibition of EGFR in meningioma caused the deactivation of STAT1 and other cancer-related pathways, eventually leading to a significant reduction in cellular proliferation." (PMID 32642677, 2020). "Conversely, in our series of meningiomas, high levels of EGFR expression were associated with a better clinical outcome, as previously reported." (PMID 22623992, 2012). "We presented our data with respect to the percent of immunoreactivity (SP) in our meningioma samples and found a significant association between percentage of immunoreactive cells staining for EGFR and histopathologic subtype." (PMID 20509969, 2010). "While radiation therapy plays an important role in the management of meningioma, an association between high EGFR expression and clinical radioresistance has been reported in patients with cancer." (PMID 20509969, 2010). "We demonstrated that meningiomas express EGFR and found that there was a significant association between the intensity of EGFR staining and tumor grade." (PMID 20509969, 2010). "The association of EGFR and meningioma grade is a potential new avenue for therapeutic intervention with selective EGFR inhibitors, either as an adjuvant treatment or in combination with radiation therapy." (PMID 20509969, 2010). "These alterations were also found in the meningioma component except for the gain of chromosome 5 of the case #10 but, interestingly, a focal amplification of EGFR appeared in the meningioma component in this case (confirmed by DNA‐methylation profiling)." (PMID 38565263, 2024). "Recent research indicates that insulin-like growth factor II (IGF-II) and epidermal growth factor receptor upregulation are vital in meningioma development." (PMID 39156289, 2024). "Alterations of other relevant genes involved in meningiomas such as gains of EGFR (found here in a primary RM case and other recurrent RM specimens) and gains of the MET gene (detected here also in one patient), appear to be infrequent in RM." (PMID 38785832, 2024). "VEGF, EGFR, EGFRvIII, PD-L1; and Sox2 expression; MGMT methylation status; and TERT promoter mutation were assessed in paired meningioma samples collected from the same patient before and after progression using immunohistochemistry and PCR." (PMID 36836440, 2023). "Here, we showed that p-ERK, EGFR was highly expressed in malignant meningioma compared to β-catenin." (PMID 37171006, 2023). "The expression of EGFR seems to be higher in low-grade meningiomas, but it is still unclear what the relation is between its expression and clinical prognosis." (PMID 37760490, 2023). "In this study, we determined the expression of EGFR vIII in meningiomas by immunohistochemical analysis of formalin-fixed and parafilm embedded tissues." (PMID 34582442, 2021). "Through this study, we indicate the antagonistic expression of the EGFR vIII as compared to the EGFR in meningiomas." (PMID 34582442, 2021). "Rather, the study poses numerous questions on the conventional findings and demands attention towards oncogenecity of EGFR vIII in meningioma." (PMID 34582442, 2021). "This study attempt the confer searches for the position attained by EGFR vIII in progression and expression of meningioma." (PMID 34582442, 2021).
meningioma (continued). "Statistical analysis proved this finding and revealed that expression of EGFR vIII is inversely correlated with tumor grades in meningioma." (PMID 34582442, 2021). "The study for the detection of EGFR vIII included Grade I (n = 34) and Grade II (n = 22) meningioma patients." (PMID 34582442, 2021). "Higher expression of EGFR vIII in low grades meningiomas as compared to high-grade tumors indicate towards its oncogenic properties." (PMID 34582442, 2021). "Further analysis by flow cytometry results supported these findings thus presented high intensity of EGFR vIII in low grades of meningioma." (PMID 34582442, 2021). "Our data reveal a significantly greater degree of EGFR vIII expression in benign tumors as compared to atypical meningioma." (PMID 34582442, 2021). "The immunohistochemical analysis combined with the FACS outcomes supports the probable capabilities of the EGFR vIII being an adequate marker for the diagnosis and treatment of meningioma tumors." (PMID 34582442, 2021). "Immunohistochemistry technique showed that EGFR vIII is highly expressed in benign tumors as compared to the atypical meningioma with a highly significant p-value (p<0.05)." (PMID 34582442, 2021). "Generally, the atypical meningioma (grade II) exhibited a low-intensity score of EGFR vIII staining, while benign meningioma (grade I) samples demonstrated a higher intensity of staining." (PMID 34582442, 2021). "We presented our data concerning the percent of immunoreactivity in meningioma samples and found a significant correlation between the percentage of immunoreactive staining for EGFR vIII and histopathologic grades." (PMID 34582442, 2021). "We demonstrated that the intensity/expression of EGFR vIII is more prominent in lower grades of meningioma." (PMID 34582442, 2021). "In a study of 25 patients with recurrent meningiomas treated with the EGFR inhibitors Gefitinib and Erlotinib." (PMID 32974188, 2020). "Our findings underline a crucial role of the EGFR and STAT1 signaling in the pathology of meningiomas and point to a therapeutic potential of its inhibition." (PMID 32642677, 2020). "STAT1 is known to be activated by EGFR, so we investigated the tyrosine kinase and found that EGFR was also constitutively phosphorylated in meningioma and was responsible for the aberrant phosphorylation of STAT1." (PMID 32642677, 2020). "Phase II trials of erlotinib or gefitinib, two targeted EGFR inhibitors, demonstrated limited efficacy in progressive meningioma patients, thought to be due to the expression of EGFR in the trial participants." (PMID 31565188, 2019). "Additional protein biomarkers that represent actionable drug targets in meningioma include EGFR, which is expressed at elevated levels in 93% of analyzed samples." (PMID 31970090, 2019). "In 25 recurrent meningioma patients treated with either erlotinib or gefitinib, both EGFR inhibitors, eight patients showed stable disease." (PMID 31970090, 2019). "Several lines of evidence support the role of EGFR signaling pathway in the pathogenesis of meningiomas." (PMID 29558515, 2018). "EGFR is expressed in 50–80% of meningiomas, and activation of the EGFR signal was shown to stimulate meningioma proliferation in vitro, further suggesting it as a potential treatment target." (PMID 29558515, 2018). "Few studies have focused on the different expression patterns of the internal and external domains of EGFR in human meningiomas." (PMID 28367377, 2017). "Despite the uniform histological appearance of meningiomas, we observed both heterogeneous immunoreactivity in the form of hotspots and homogeneous EGFR immunoreactivity, pointing to meningiomas as heterogeneous in this regard." (PMID 28367377, 2017). "Both membranous and cytoplasmic EGFR immunoreactivity were observed in the meningioma tissue, however, membranous reactivity dominated in most cases for both the ECD and ICD." (PMID 28367377, 2017).
meningioma (continued). "EGFR and its ligands are frequently overexpressed in human meningiomas compared with normal meninges, and the receptor is generally in an activated state." (PMID 28367377, 2017). "As such, immunohistochemistry appears as a reliable and practical method to determine EGFR expression in meningioma tissue." (PMID 28367377, 2017). "Both membranous and cytoplasmic EGFR immunoreactivity have been described in meningiomas, however, the prognostic relevance is scarcely described." (PMID 28367377, 2017). "The epithelial growth factor receptor (EGFR) is one of the most extensively studied molecular targets for anti-cancer therapy and is also considered as a target for meningioma treatment." (PMID 24932282, 2014). "Based on this background, two of the low molecular weight anti-EGFR inhibitors, gefitinib and erlotinib, were introduced in phase II clinical trials in patients with recurrent meningioma (North American Brain Tumor Consortium Trials 00–01 and 01–03)." (PMID 24932282, 2014). "The present study aimed to assess the occurrence of the mutations in the EGFR TK domain and in the selected downstream genes, KRAS, BRAF and PIK3CA, in a relatively large group of meningioma patients." (PMID 24932282, 2014). "In total, 55 formalin-fixed, paraffin-embedded meningioma samples were subjected to genomic sequencing of EGFR (exons 18–21), KRAS (exon 1), BRAF (exon 15) and PI3K (exons 9, 20)." (PMID 24932282, 2014). "In the IOMM-Lee meningioma cell line, the EGFR pathway was shown to be involved in radiation-induced progression." (PMID 24932282, 2014). "Some studies reported higher EGFR protein levels in grade I and grade II meningiomas compared to grade III meningiomas." (PMID 22623992, 2012). "EGFR has been reported to be expressed in meningiomas at frequencies greater than 60% and even as high as 100%, which is similar to our results with ECD-Ab but not with ICD-Ab." (PMID 22623992, 2012). "It has been suggested that the EGFR pathway in meningiomas is stimulated by an autocrine/paracrine mechanism that occurs in association with other control systems." (PMID 22623992, 2012). "Regarding the roles of the EGFR pathway in oncogenesis, the expression pattern of this receptor in meningiomas seems somewhat paradoxical." (PMID 22623992, 2012). "That suggests that the EGFR b, c and d isoforms are likely to be produced by meningiomas and supports our immunohistochemical results." (PMID 22623992, 2012). "All meningiomas expressed EGFR v1, v3 and v4 mRNA whereas only 50% of the tumors expressed EGFRv2 mRNA." (PMID 22623992, 2012). "In meningiomas, intracellular EGFR inhibitors, like Gefitinib or Erlotinib have been shown to be inefficient." (PMID 22623992, 2012). "sEGFR have a potential role in activating or inhibiting the EGFR pathway and their expression pattern can be of major interest for potential therapeutic applications in meningioma." (PMID 22623992, 2012). "The rationale for combination of inhibitors of EGFR with ionizing radiation is, therefore, a potentially attractive combination for recurrent or benign meningioma." (PMID 20509969, 2010). "Our data demonstrate significantly greater degree of EGFR expression in benign and atypical meningiomas as compared to the malignant meningiomas." (PMID 20509969, 2010). "Some investigators, utilizing ligand-binding techniques, demonstrated a broad range of EGFR expression in meningiomas, varying from approximately 30% to 100%." (PMID 20509969, 2010). "Generally, the malignant meningiomas exhibited very low scores of intensity of EGFR staining, while benign and atypical samples demonstrated a higher intensity of staining." (PMID 20509969, 2010). "The present study represents the largest series evaluating EGFR expression in meningiomas in the literature to date." (PMID 20509969, 2010). "Recently, an interest emerged in assessing expression of EGFR in CNS malignancies such as meningiomas, gliomas, etc." (PMID 20509969, 2010).